AMDHD2 (amidohydrolase domain containing 2)
Description:
Hydrolyzes the N-glycolyl group from N-glycolylglucosamine 6-phosphate (GlcNGc-6-P) in the N-glycolylneuraminic acid (Neu5Gc) degradation pathway. Although human is not able to catalyze formation of Neu5Gc due to the inactive CMAHP enzyme, Neu5Gc is present in food and must be degraded.
Synonyms: CGI-14
Tractability: Small molecule: a structure with a bound ligand is known. PROTAC: ubiquitination databases record sites on it; its protein half-life has been measured; a small molecule that binds it is known.
Target class: Enzyme; Hydrolase
Gene: Protein-coding gene on chromosome 16 (2,520,340 to 2,531,422, forward strand). Ensembl gene ENSG00000162066.
Subcellular location (Human Protein Atlas): Cytosol; Nucleoli
Pathways (Reactome):
Metabolism of proteins: Synthesis of UDP-N-acetyl-glucosamine
Gene Ontology:
Molecular function: N-acetylgalactosamine-6-phosphate deacetylase activity; N-acetylglucosamine-6-phosphate deacetylase activity; protein binding; hydrolase activity; hydrolase activity, acting on carbon-nitrogen (but not peptide) bonds
Biological process: negative regulation of UDP-N-acetylglucosamine biosynthetic process; N-acetylglucosamine catabolic process; N-acetylneuraminate catabolic process; UDP-N-acetylglucosamine biosynthetic process; N-acetylglucosamine metabolic process
Cellular component: nucleus; cytosol
Genetic constraint (gnomAD): Loss-of-function variants: 24 observed, 38.89 expected, observed/expected ratio (o/e) 0.62, 90% interval 0.45 to 0.87. The synonymous counts are far from expectation, so gnomAD's model fits this gene poorly and the ratio says little. Missense variants: 540 observed, 565.63 expected, observed/expected ratio (o/e) 0.95, 90% interval 0.89 to 1.02. Synonymous variants: 332 observed, 247.35 expected, observed/expected ratio (o/e) 1.34, 90% interval 1.23 to 1.47.
Homologues: Orthologues: chimpanzee AMDHD2 (98% identical), dog AMDHD2 (92% identical), rabbit AMDHD2 (92% identical), pig AMDHD2 (91% identical), mouse Amdhd2 (91% identical), rat Amdhd2 (90% identical), guinea pig AMDHD2 (89% identical), tropical clawed frog amdhd2 (70% identical), zebrafish amdhd2 (67% identical), Drosophila melanogaster CG17065 (58% identical), Caenorhabditis elegans F59B2.3 (50% identical).
Diseases named in the same sentence as AMDHD2 in open-access papers:
AMDHD2 is named in the same sentence as 5 diseases in open-access papers, as found by Europe PMC text mining. Sharing a sentence is not in itself a finding about the gene and the disease. The quoted sentences say what the papers report.
colon cancer (1 paper, 2017). "TYMS, SHMT2, GALT, RENBP, and AMDHD2 were among the metabolic genes that had an unfavorable expression in colon cancer, meaning that their high expression in patients treated with 5-FU was associated with poorer prognosis." (PMID 29026541, 2017).
AMDHD2 also shares sentences with these, for which no sentence is quoted: cancer (1 paper); epilepsy (1); immune dysfunction (1); tumours (1).